MTOR (mechanistic target of rapamycin kinase)
Diseases named in the same sentence as MTOR in open-access papers (continued):
Sharing a sentence is not in itself a finding about the gene and the disease.
tumor (continued). "Overexpressed mTOR, Met, CHC, and DDR1 were verified in HCC tumor tissues, as compared with precursor and normal liver tissues." (PMID 25861255, 2015). "We demonstrated that miR-99b-5p functions as a tumor suppressing miRNA in metastatic CRC, and that its suppressive effects are mediated chiefly by suppressing mTOR expression." (PMID 26259252, 2015). "IHC analysis in paired tumor and normal pancreatic tissues also found significantly higher levels of phosphorylated AKT and mTOR in tumors than in normal tissues." (PMID 25793983, 2015). "The first is the activation of the EGFR/PI3K/Akt/mTOR signaling pathway in GBM cells, a key signaling factor in the development of GBM mediating tumor proliferation." (PMID 26110872, 2015). "AMPK monitors and maintains energy homeostasis at the cellular level; because AMPK primarily acts as a component of the LKB1 tumor suppressor cascade upstream of the TSC1/2/mTOR pathway, AMPK is likely to be a tumor suppressor." (PMID 25798539, 2015). "The data presented here demonstrate that the RCC cells regained full responsiveness to the mTOR-inhibitor RAD001, whereas the TKI-inhibitor sorafenib was only partially effective in blocking tumour growth." (PMID 25444514, 2015). "Their target prediction and pathway analysis showed that miR-126 can regulate key molecules and critical pathways involved in ccRCC tumor development and progression, including the IGF1R, BCL2, HIF-1, VEGF, mTOR, and PI3K-Akt signaling pathways." (PMID 26416448, 2015). "Concurrent use of mTOR inhibitors such as rapamycin and RAD001 and standard-of-care cisplatin/radiation therapy (CRT) has been applied in HPV(+) HNSCC and CCSCC tumour xenografts and mouse models for evaluating the preclinical efficacy of mTOR inhibition." (PMID 26022660, 2015). "Pooled tumor lysates from regorafenib- and vehicle-treated mice were analyzed for the effects of regorafenib on selected proteins involved in the MAPK and AKT/mTOR signaling pathways and for selected proteins involved in the cell cycle." (PMID 26514182, 2015). "This point is disputed, however, since previous works reported that a potential interaction between mTOR and IKKα triggers NFkB in tumor cells and constitutive activation of the PI3K/Akt/mTOR pathway." (PMID 26468083, 2015). "The immune-reactivity scores for the expression of mTOR and p-mTOR as well as for MMP2, MMP7, and MMP9 in the tumor center correlated each with its expression at the invasive front (p < 0.001)." (PMID 26652716, 2015). "In this regard, it is unsurprising that Akt is considered a signaling hub for tumor cells and the PI3K/Akt/mTOR pathway in particular has been the interest of targeted drug development." (PMID 26793165, 2015). "Taken together, these results indicate miR-7 acts as a tumor suppressor in ACC by affecting multiple molecular targets, involved in the mTOR and MAPK signalling pathways." (PMID 26452132, 2015). "In recent clinical study reports, activation of PI3K/Akt/mTOR and MAPK/ERK pathways is correlated with tumor progression and worse survival of patients." (PMID 25004403, 2014). "Given the importance of mTOR and DUSP/MKP signaling in tumor growth and drug resistance, a further detailed understanding of the signaling relationships linking these two pathways is warranted to effectively target these signaling cascades." (PMID 25568665, 2014). "Eighteen patients provided tumor tissue specimens for the IHC staining of phospho-AKT, phospho-mTOR, phospho-S6RP and phospho-4EBP1, and graded as described." (PMID 24886512, 2014). "Activation of this pathway is usually determined by immunohistochemical studies of protein phosphorylation in HCC tumor tissue, because genetic aberrations of IGFR and PI3K/Akt/mTOR pathways are rare in HCC." (PMID 24387108, 2014). "The altered phosphorylation of Akt and mTOR in HED and CRD tumors correlated with the corresponding levels of insulin and IGF-1 and the tumor growth observed in the respective groups." (PMID 25026276, 2014).
tumor (continued). "Current studies show a link between mTOR and E2-induced tumorigenesis and cellular proliferation where RAD001 is capable of suppressing E2-induced tumor growth and cellular proliferation." (PMID 25283550, 2014). "NVP-BEZ235 is a dual inhibitor of both PI3K and mTOR and promotes the degradation of MYCN to effectively reduce tumor burden in the MYCN transgenic mouse via GSK3β activation." (PMID 24391509, 2014). "Basic research studies have demonstrated the tumor-suppressor function for miR-100, regulating several oncogenes, such as insulin-like growth factor 2 (IGF2) and mechanistic target of rapamycin (mTOR)." (PMID 25309903, 2014). "Our data that treatment of RD and RH30 cells with chemotherapeutic drug vincristine and mTOR inhibitors temsirolimus and rapamycin augments the ability of GANT-61 for enhanced killing of these tumor cells supports this notion." (PMID 25432075, 2014). "To gain further insight into the molecular mechanism of the inhibitory effects of YLT192 on tumor cells we evaluated the expression of p44/42 MAPK, STAT3, AKT, and mammalian target of rapamycin (mTOR) in U251 and HCT116 cells 48 h after treatment." (PMID 25112436, 2014). "Phorbol ester is the most well known tumor promoter, which activates MEK/ERK and mTOR/S6K signaling pathways." (PMID 25587030, 2014). "Tumor cells taken from patients with TSC have been shown to exhibit active mammalian target of the rapamycin (mTOR) signaling, so mTOR inhibitors have been identified as potential therapeutic agents." (PMID 24612911, 2014). "HIF-1α stabilization in normoxia can be due to sustained activation of the mTOR pathway, which was previously shown to be responsible for regulating the translation of HIF-1α mRNA in other tumor types." (PMID 25166211, 2014). "When coupled with mTOR inhibition, not only would there be a decrease in MGMT levels, but the tumour cell would be compromised in its ability to synthesise new protein, thus sensitising the cells to further TMZ treatment." (PMID 24909675, 2014). "Immunohistochemistry analysis revealed that tumor sections from peritoneum and adipose sites of HED group showed higher phosphorylation of Akt (pAkt) and phosphorylated mTOR (pmTOR) compared to RD and CRD groups." (PMID 25026276, 2014). "A previous study reported that mTOR, an important downstream target of PI3K/AKT, can also increase HIF-1α-dependent gene expression in certain tumor cell types." (PMID 24722367, 2014). "As an mTOR inhibitor, rapamycin can reduce FDG and fluorothymidine uptake in tumour xenografts derived from sensitive tumour cell lines." (PMID 25283154, 2014). "This study shows that miR-382 upregulation by hypoxia participates in hypoxia-induced angiogenesis, and in particular, miR-382 directly targets PTEN, a tumor suppressor, and stimulates the AKT/mTOR signaling pathway." (PMID 24914051, 2014). "Combined treatment with crizotinib and an ATP-competitive mTOR inhibitor abrogated RPS6 phosphorylation, leading to reduced tumor growth and prolonged survival in ALKF1174L/MYCN-positive models compared to single agent treatment." (PMID 25228590, 2014). "Results revealed that the anti-tumor and angiostatic effects of thioridazine were regulated by reducing the phosphorylation of VEGFR-2 and inhibiting PI3K/mTOR signaling." (PMID 24952635, 2014). "Consistent with our findings, miR-375, known as a tumor suppressive gene, was reported to target PDK1, leading to the inhibition of PDK1/AKT/MTOR pathway and thus promotion of autophagy." (PMID 25333253, 2014). "We observed that mTOR inhibitor treatment exerted a greater decrease in 4EBP1 phosphorylation (62%) than in S6K1 phosphorylation (33%), although individual tumor responses varied." (PMID 24708766, 2014). "Taken together, the combination of a HSP90AA1 inhibitor and a MTOR inhibitor not only activates autophagy, leading to KIT downregulation, but also likely exerts anti-angiogenic effects that to contribute to tumor growth inhibition in vivo in our study." (PMID 25375091, 2014).
tumor (continued). "NVP-BEZ235 inhibits PI3K/Akt and mTOR (TORC1 and TORC2); thus, it efficiently reduces tumor growth in in vivo models." (PMID 24743574, 2014). "MID1, a negative regulator of the tumor-suppressor PP2A, is known to promote PI3K, mTOR, NFκB and Hh signaling." (PMID 24913494, 2014). "Despite strong preclinical evidence to support co-targeting of the PI3K/mTOR and MAPK pathways in several tumor types, early results of clinical trials have demonstrated mixed success." (PMID 25401499, 2014). "Growth and apoptosis of tumor xenografts were examined, and the expression levels of genes and proteins involved in the PI3K/Akt/mTOR pathway were measured by RT-PCR and western blotting, respectively." (PMID 25005526, 2014). "This study evaluated the combination of a PI3K/mTOR inhibitor (PF-04691502/PF-502) in combination with a MEK inhibitor (PD-0325901/PD-901) in CRC cell lines and patient-derived CRC tumor xenograft models (PDTX)." (PMID 25401499, 2014). "The combined treatment using mTOR inhibitors and IGF-1R antibody/inhibitor has been proved to enhance the anti-tumor effect of mTOR inhibitors." (PMID 25026290, 2014). "Most of these studies have attributed the tumor inhibitory effect of CR to the deceased circulating levels of insulin and IGF-1 and inhibition in its subsequent downstream signaling of PI3K/Akt-mTOR." (PMID 25026276, 2014). "Erk1-2 in turn promotes the activation of mTOR signaling, known to regulate HIF-1α protein translation and tumor growth." (PMID 25166211, 2014). "In vitro experiments have demonstrated that adiponectin can inhibit tumor growth via activating AMP-activated protein kinase (AMPK), thereby downregulating mammalian target of rapamycin (mTOR) pathways." (PMID 25069390, 2014). "Our study demonstrated that metformin effectively downregulates mTOR components including phospho-AKT, phospho-S6, phospho-70S6 which are important factors maintain tumor cell growth." (PMID 24859412, 2014). "The decrease in mTOR expression following NAC was found to positively correlate with HER2 expression and the reduction of tumor sizes." (PMID 25364442, 2014). "Therefore, the mTOR inhibitor may be a potential candidate for the treatment of this type of tumor." (PMID 24348822, 2014). "Increasing evidence indicates that the Akt/mTOR pathway is frequently activated in MPM and plays a key role in tumor aggressiveness and chemoresistance." (PMID 25026285, 2014). "For instance, PTEN, a well-characterized human tumor suppressor gene, is an antagonist of the PI3K/Akt/mTOR pathway." (PMID 24796583, 2014). "These bidirectional effects on mTOR and BAD in HCC tissues were in agreement with the survival, aggressive, metastatic, and antiapoptotic effects of tumor cells." (PMID 25243186, 2014). "The expression of p-mTOR and p-4E-BP1 pre- and post-NAC was also evaluated, as well as the expression change of the two factors to identify correlations with tumor size." (PMID 25364442, 2014). "We treated mice with the mTOR inhibitor AZD8055 (20mg kg−1) and found that inhibition of mTORC1 and mTORC2 significantly inhibited tumor growth (4.72 ± 1.19, n=3 mean ± SD, P<0.001) compared with Vehicle treated mice." (PMID 25436981, 2014). "Combined mammalian target of Rapamycin (mTOR) and histone deacetylase (HDAC) inhibition has been shown not only to enhance anti-tumour potential, but also to prevent resistance development seen under mono-drug therapy." (PMID 24779401, 2014). "Twelve of the fifteen miRNAs significantly upregulated with combination treatment possess tumor suppressor properties, and thus, this study suggests miRNAs for further functional study that may be involved in the mechanism of action and clinical activity of combined mTOR and VEGF inhibition." (PMID 24047116, 2013).
tumor (continued). "Human colon cancers xenografted in nude mice treated with the combination of low doses irinotecan and rapamycin showed a potent inhibition of the mTOR/HIF-1α axis, which was accompanied by a dramatic reduction in tumor volume, compared to single agent." (PMID 24216984, 2013). "To explicate mechanisms of tumor resistance, we compared patient #2 with two EWS patients (patients 3&4) who initially responded to IGF1R+mTOR inhibitor therapy." (PMID 23922674, 2013). "Total RNA was extracted from tumor lysates and PI3K/AKT/mTOR PCR arrays were conducted to determine Reishi effects on genes involved in this pro-survival pathway." (PMID 23468988, 2013). "Although simultaneous inhibition of MTOR and HDAC exerts profound anti-tumor properties, the possible interaction and therapeutic mechanism of this combination remain to be defined in BL." (PMID 23866964, 2013). "In turn, rapalog-mediated inhibition of mTOR increases ERK activation both in vitro and in tumor biopsies from patients treated as part of a clinical trial." (PMID 24392034, 2013). "Several signaling pathways are involved in tumor angiogenesis, such as VEGF, which plays a crucial role in RCC carcinogenesis, PDGF, the mammalian target of rapamycin (mTOR), VHL, a tumor suppressor gene, and HIF." (PMID 24093097, 2013). "In consistence with our findings, dysregulated miR-7 is recently detected in tumor tissues from HCC patients and functions in suppressing cell growth by targeting Akt/mTOR, a survival signaling pathway downstream of EGFR." (PMID 23840262, 2013). "Our findings are the first to show that Reishi downregulates the expression of PI3K/AKT/mTOR and also MAPK pathway effector genes and proteins in vitro and in vivo, and it significantly reduces IBC tumor growth and weight." (PMID 23468988, 2013). "Reduction of [18F]FLT uptake in the tumor has also been used as imaging biomarker to predict overall survival of patients with GBM treated with bevacizumab, irinotecan and an mTor inhibitor." (PMID 23861829, 2013). "We observed that D-PDMP markedly decreased mTOR protein expression, suggesting that by inhibiting angiogenesis, D-PDMP deprived the tumor of blood supply and thus contributed to a reduction in tumor volume." (PMID 23671696, 2013). "Conversely, inhibitors of the PI3K/AKT/mTOR pathway, in particular the mTOR inhibitor temsirolimus (CCI-779), induce autophagy, which can promote tumor survival and thus, these agents potentially limit their own efficacy." (PMID 23383069, 2013). "The mammalian target of rapamycin (mTOR), a kinase acting downstream of the PI3K/AKT signaling pathway, is a critical regulator of basic cellular functions and plays an important role in tumor progression." (PMID 24009623, 2013). "In this study, we set out to dissect the BCR-ABL1-PI3K/AKT/mTOR pathway to further investigate TKI resistance mechanisms and sensitization of resistant tumor cells to TKI treatment." (PMID 24349524, 2013). "Through the regulation of translation or by directly influencing the activity of p70S6K, mTOR can induce the antiapoptotic functions of mitochondrial proteins, e.g. by BAD phosphorylation, supporting the survival and proliferation of tumor cells." (PMID 23693095, 2013). "Feeding D-PDMP markedly reduced tumor volume by way of decreasing the enzymatic activity of LCS, LCS mass, and consequently LacCer mass, and the angiogenic proteins such as p-AKT-1 and mTOR." (PMID 23671696, 2013). "Taken together, hyper-activation of the AKT/mTOR pathway that occurs at a wide range of UVA and UVB doses supports epidermal tumor promotion by enforcing cell cycle transition and accelerated proliferation." (PMID 23887651, 2013). "Nab-paclitaxel treatment increased expression of p-mTOR and p-4E-BP1 in cultured SNU16 cells and in SNU16 tumor tissues as observed by immunostaining." (PMID 24042258, 2013).
tumor (continued). "Clinically relevant agents that influence mTOR or UPR signaling include for example imatinib, nelfinavir and sunitinib, which can improve tumor oxygenation and inhibit angiogenesis." (PMID 24152759, 2013). "Mammalian target of rapamycin (mTOR) is overexpressed in TNBC and it represents a potential target for the treatment of this aggressive tumour." (PMID 23587222, 2013). "Mechanically, we found AKT/mTOR, ERK, as well as JAK2/STAT3 pathways account for the anti-tumor effects of simvastatin." (PMID 23690956, 2013). "In the models we studied, optimal blockade of tumor growth and metastatic spread was only achieved by combining an FGFR inhibitor with the PI3K/mTOR inhibitor or with the pan-ErbB inhibitor." (PMID 23343422, 2013). "In this study, we set out to dissect the PI3K/AKT/mammalian target of rapamycin (mTOR) pathway to investigate TKI resistance mechanisms and sensitization of Ph+ tumor cells to TKI treatment." (PMID 24349524, 2013). "mTOR interferes with hypoxia-inducible factor-1α (HIF-1α), a key transcription factor with a pivotal role in tumor cell metabolism." (PMID 24216984, 2013). "Activated AKT triggers downstream mTOR/p70S6K1 signaling resulting in the induction of pro-angiogenic factors such as VEGF and b-FGF, thereby inducing neovascularization to promote tumor growth." (PMID 23301033, 2013). "As we show here, the PI3K/mTOR inhibitor NVP-BEZ235 robustly blocks this pathway and the combination of dovitinib + NVP-BEZ235 had significantly better anti-tumor and anti-metastatic activity than treatment with single inhibitors." (PMID 23343422, 2013). "Chemopreventive experiments using mTOR inhibitor-rapamycin treatment significantly delayed the onset of the ASCC tumors and reduced the tumor burden in 2cKO mice by decreasing the phosphorylation of Akt and S6." (PMID 24124460, 2013). "However, tumor weights were significantly smaller in animals treated with everolimus fed the 7% protein diet than in those treated with everolimus fed the 20% protein diet, suggesting that protein restriction and mTOR inhibition have additive inhibitory effects on PCa development." (PMID 24353195, 2013). "The mammalian target of rapamycin (mTOR), which is located in the downstream of the phosphatidylinositol 3 kinase AKT pathway, is a key regulator of growth and proliferation of tumor cells." (PMID 24403259, 2013). "Previously, we identified several tumor-suppressive miRNAs that are repressed in c-Src–transformed cells: miR-99a targets mTOR to suppress tumor progression, and miR-542-3p targets ILK to suppress tumor malignancy." (PMID 24244675, 2013). "The present study was designed to elucidate the anti-tumor effects of Reishi utilizing in vivo and in vitro IBC models focusing on the PI3K/AKT/mTOR pathways and effectors." (PMID 23468988, 2013). "This study correlated the presence of mTOR with the expression of HIF1α and VEGF, both of which are important for tumor angiogenesis." (PMID 23155381, 2012). "Unfortunately, the median duration of EW response was only 5–7 months, probably because tumour cells escape IGF-1R inhibition, through AKT or through activation of other signalling pathways (e.g., other TK receptors, mTOR)." (PMID 23226965, 2012). "In the tumor tissues excised from AST-treated animals, protein level of p-Akt, p-mTOR, VEGF, VEGFR1 and VEGFR2 was down-regulated." (PMID 22992293, 2012). "This case report suggests that anti-VEGF agents such as sunitinib and mTOR-targeted agents such as everolimus are effective and appropriate treatments for this RCC tumor subtype." (PMID 22524151, 2012). "Results show that the decrease of VEGF expression in tumor tissue of AST-treated mice was correlated with the downregulation of p-Akt, p-mTOR and COX-2, which are consistent with the in vitro findings." (PMID 22992293, 2012). "For these tumours, evidence derived from in vitro analysis suggests that resistance can be overcome by coupling anti-EGFR-agents with mTOR inhibitors." (PMID 22240798, 2012).